PRLR (prolactin receptor)
Diseases named in the same sentence as PRLR in open-access papers (continued):
Sharing a sentence is not in itself a finding about the gene and the disease.
tumor (continued). "For example, anti-inflammatory therapies could simultaneously mitigate PRLR’s role in inflammatory responses and suppress the deterioration of the tumor microenvironment." (PMID 40978029, 2025). "Therefore, suppressing both GHR and PRLR by a dual antagonist like compound-D or S1H can have a wider range of anti-tumor effects than GHR-specific inhibition by pegvisomant." (PMID 41515995, 2025). "Tumor expression of PRLR, STAT5 and JAK2 was read manually by pathologist that may have led to measurement error; therefore, future studies should consider using image analysis to reduce subjectivity." (PMID 36882838, 2023). "All these results suggested that tumor immune infiltration might partially explain the roles of PRLR in BC." (PMID 36556307, 2022). "The co-expression of PRLR and ERα in a non-compliant, rigid matrix is associated with increased tumor invasiveness and reduced responsiveness to estrogen antagonists." (PMID 36187116, 2022). "Beyond ER itself, an increasing number of studies have also suggested that the crosstalk between prolactin receptor (PRLR) with ER and EGFR/HER2 pathways plays a crucial role inducing tumour proliferation and thus be associated with resistance to anti-HER2 treatment and with higher risk of relapse." (PMID 35884366, 2022). "In addition, the comparative analysis of paired syndromic neoplasms revealed several growth pathways susceptible to therapeutic intervention by PARP, PRLR, and selective receptor tyrosine kinase (RTK) inhibitors." (PMID 35978432, 2022). "A microarray analysis performed with MCF7 BC cells showed that the binding of PRL with PRLR could induce the 1.2-fold upregulation of approximately 4,700 genes, which are involved in the activation of pathways related to neoplasm proliferation and progression." (PMID 34745013, 2021). "PRLR-SF exerts a tumor-suppressive role in PDAC by preventing PPP metabolism." (PMID 33664869, 2021). "A possible direct and indirect effect might be performed by HCMV because most of the HCMV-cells in the tumor expressed PRLR." (PMID 34745013, 2021). "Additionally, several tumor cell lines with lower levels of PRLR were sensitive to killing by the PBD conjugate but were largely insensitive to h16f-MMAE." (PMID 34107902, 2021). "PDAC cell lines that overexpressed PRLR-SF formed significantly smaller xenograft tumors in mice (based on the tumor weights) than PDAC cells transduced with a control vector and had a lower proliferation index (based on staining for proliferating cell nuclear antigen)." (PMID 33664869, 2021). "Consequently, upon loss of PRLR expression cancer cells dedifferentiation leads to increased tumor CSC content, further contributing to tumor heterogeneity, metastasis, and resistance to therapy." (PMID 33446633, 2021). "Patients could be identified as candidates for targeted PRLR therapy by conducting an immunochemical analysis of tumor biopsies for isoform-specific PRLR with presently available selective antibodies." (PMID 34071395, 2021). "We believe the tumor micro-environment may be responsible for directing a particular PRLR signaling pathway of choice." (PMID 34572912, 2021). "BT-474 is a low PRLR-expressing tumor cell line with ~ 10,000 receptors per cell." (PMID 34107902, 2021). "Based on results from mouse xenograft tumor models, these properties translate into a highly active therapeutic with activity extending to those tumors with low PRLR expression - as few as 10,000 receptors per cell - which is notably below levels typically present on tumor cells targeted by ADCs." (PMID 34107902, 2021). "Elevated expression of PRLR in tumor versus normal breast tissue may enable an acceptable therapeutic window for PRLR ADCs." (PMID 34107902, 2021). "Subcutaneous tumor mouse models were used to analyze the in vivo anti-tumor effects of PRLR-DbsAb." (PMID 32398042, 2020). "Mice with PRLR-DbsAb showed a better tumor inhibition and survival." (PMID 32398042, 2020).
tumor (continued). "Combined with PD-1 mAb, the best killing activity reached to 55%, which demonstrated blockade of PD-1 might enhance the PRLR-DbsAb-mediated cytotoxicity of against tumor cells with high level of PD-L1." (PMID 32398042, 2020). "In conclusion, PRLR-DbsAb could stimulate the infiltration of effector T cells as well as the expression of PD-L1 for tumor cells." (PMID 32398042, 2020). "Of note, a majority of HCMV-positive cells within the tumor tissue specimens were expressing PRLR." (PMID 32121009, 2020). "Activation of these pathways is a well-known phenomenon in HCMV-infected cells and HCMV-induced function of the PRL/PRLR axis may therefore result in increased cellular proliferation and tumor progression via binding to the highly abundant PRLR in tumors." (PMID 32121009, 2020). "The results of ex vivo experiments showed that the immunotherapeutic bispecific antibody PRLR-DbsAb may suppress the immune response by upregulating PD-L1 in lymphocyte besides PD-L1 in tumor." (PMID 32398042, 2020). "It has been found that, as in CC, there is an autocrine secretion of prolactin in the tumor cells, and the activation of PRLR triggers the signaling pathway of Src-ERK-AKT and phosphorylate the ERα inducing the activation and recruitment of the receptor to the ERE." (PMID 31507337, 2019). "Our findings suggest that the activation of the PRL/PRLR pathway may facilitate GBM tumour progression." (PMID 31862900, 2019). "Although circulating PRL may play a role in the pathogenesis of GBM, expression of PRL and PRLR in the tumour microenvironment may exert autocrine/paracrine effects that modulate GBM cell behaviour." (PMID 31862900, 2019). "In addition, the level of co-expression between TGFβ receptors and PRLR was found to decrease with tumor progression, more advanced stages of the disease and lymph node (LN)-positive tumors." (PMID 30987013, 2019). "Therefore, the profile of PRLR and TGFβ receptors co-expression in relation to tumor grade were examined using the same clinical cases used in the tissue microarray (TMA) above." (PMID 30987013, 2019). "Approximately, 66% of GBM patients had PrlR-positive cells in their tumours." (PMID 27788487, 2016). "We have shown that physical rigidity of the ECM is a major determinant of the spectrum of PRL-induced signals, increasing PRL activation of the tumor progressive FAK/SFK/ERK1/2 signaling cascade in stiff environments through localization of PRLR to focal adhesions." (PMID 27344177, 2016). "Together, these data suggest that PRLR/focal adhesion signals may be enhanced by co-localization of these components in lipid rich areas, leading to activation of pro-tumor progressive signals." (PMID 27344177, 2016). "PRLR-staining pattern was heterogeneous and mainly localized in certain tumor regions." (PMID 24257371, 2013). "Validation of PRLR up-regulation in ES + Tum tissue sections by immunohistochemistry revealed a heterogeneous staining pattern with an intensive PRLR staining localized in well-defined tumor regions." (PMID 24257371, 2013). "In addition the 80 kDa isoform was observed at levels similar to the 60/70 kD PRLr in 10 tumours or weaker in 15 tumours." (PMID 22606260, 2012). "As different isoforms of the PRLr have been shown to be differentially expressed and localized to diverse parts of the cell in various tumours, we aimed to characterize the sub-cellular localization as well as the overall expression of the PRLr using immunohistochemistry." (PMID 22606260, 2012). "Also, 58 out of 81 (72%) patients with tumours with high PRLR expression and 3 out of 8 (38%) patients with tumours showing low PRLR expression died during the follow-up period (P=0.023, log-rank test)." (PMID 21505459, 2011). "To evaluate whether PRLR expression is associated with the outcome of patients with SCCHN, we determined PRLR expression by immunohistochemistry in a larger set of human SCCHN tumour samples." (PMID 21505459, 2011).
tumor (continued). "In addition to this classical PRLR-dependent signal transduction pathway, PRLR exerts tumour-promoting effects by activating numerous other molecular mechanisms." (PMID 21505459, 2011). "Immunoreactivity for PRLR was observed in 85 out of 89 (95%) tumours." (PMID 21505459, 2011). "Therefore, tumours with high levels of prolactin would perhaps be more efficiently treated with additional antiprolactin/prolactin receptor therapies." (PMID 15213724, 2004). "Therefore, PRLR may influence patient prognosis by activating inflammation-related pathways that reshape the tumor microenvironment." (PMID 40978029, 2025). "Moreover, PRLR-DbsAb stimulated T-cell infiltration and expression of PD-L1 in these tumor tissues." (PMID 36714582, 2022). "Once the additional validation and optimization steps are accomplished, we foresee that SMI-6 could provide a triple benefit to BC patients with PRL/PRLR-expressing tumors: suppression of tumor growth, inhibition of invasion/metastasis, and enhanced efficacy of standard chemotherapeutic agents." (PMID 34071395, 2021). "Therefore, to examine exclusively the effect of loss PRLR expression on tumor development in vivo we chose not to supplement the mice with estrogen." (PMID 33446633, 2021). "Immunotherapy may be a promising treatment against the tumor target of PRLR." (PMID 32398042, 2020). "Moreover, PRLR-DbsAb could significantly inhibit the volume and weight of T47D derived-tumor and the effect was dose dependent." (PMID 32398042, 2020). "On the other hand, it is known that the alone expression of ERα or PRLR is not related to affect the progression of the tumor, whereas the co-expression of both receptors is associated to the induction of invasion and a reduced response to estrogen antagonists." (PMID 31507337, 2019). "Thus, it is conceivable that some of EGF actions could result from the activation of PRLR by endogenous prolactin expressed in tumor cells." (PMID 27564112, 2016). "However, in our study PrlR was also expressed at different levels in cancer-adjacent normal brain tissues, which emphasize a possible indirect effect of the tumor micro-environment on these sites that may affect the expression of PrlR." (PMID 27788487, 2016). "Moreover, within the MDA-MB-231/PRLR untreated group only one mouse showed tumor growth that reached a maximum volume of 0.875 mm3 suggesting that mouse PRL while it is described as a weak agonist of the hPRLR, it is sufficient to induce activation of the overexpressed hPRLR." (PMID 27480353, 2016). "Evidence also highlights PRLR’s role in various cancers, acting through pathways like JAK2/STAT3 to regulate tumor cell proliferation, survival, invasion, and immune evasion." (PMID 40978029, 2025). "By downregulating PRLR, Osthole disrupts the ligand-dependent activation of JAK2, leading to reduced STAT3 phosphorylation — a critical event in tumor cell proliferation and resistance to apoptosis." (PMID 40978029, 2025). "PRLR is known to activate multiple downstream signaling pathways, among which the JAK2/STAT3 pathway plays a crucial role in tumor cell proliferation, immune evasion, and therapeutic resistance." (PMID 40978029, 2025). "Other studies have found that these factors can also affect the prognosis of TNBC, including tumor-infiltrating lymphocytes (TILs), CD103 iTIL density, positive prolactin receptor, adipophilin, erythropoietin receptor and increased Bcl-2 expression." (PMID 38827797, 2024). "Similar to the chemoresistance-induced senescence resilient phenotype where ATR catalytic activity enables the induction of this cellular state, tumor survival and persistence, ATR was also involved in the PRLR-mediated resistance to cytarabine." (PMID 37208719, 2023). "For example, ADCs with bispecific antibodies targeting HER-2 and the prolactin receptor have been shown to improve ADC internalisation and have higher anti-tumour activity in vitro compared to a conventional HER2-directed ADC." (PMID 37631232, 2023).
tumor (continued). "The inhibition of the PRLR activation by locally produced PRL showed that local PRL acts as a proapoptotic and antiproliferative factor in both primary cultures and the tumor-derived GH3 cell line." (PMID 36714572, 2022). "We then explored the relationship between PRLR, CACNA2D1, and tumor immunity by looking at tumor immune cell infiltration and immune checkpoints." (PMID 36556307, 2022). "Therefore, we theorized that PRLR might bear a relationship with tumor immunity of BC." (PMID 36556307, 2022). "Some investigators have challenged the concept of the tumor-promoting actions of PRL, arguing that elevated PRL and/or high expression of the PRLR can actually serve as markers of favorable clinic-pathological parameters and better patient survival." (PMID 34071395, 2021). "Despite low PRLR expression (0.09x total PRLR as MCF7), HepG2 had tumor growth delay (p < 0.001 compared to vehicle, p < 0.005 compared to Co-PBD) when treated with ABBV-176 at 0.2 mg/kg Q7D × 3 as shown in the survival chart." (PMID 34107902, 2021). "The crosstalk between PRLR and EGFR/HER2 signaling is an additional route that magnifies the actions of their ligands, and further promote tumor growth." (PMID 34572912, 2021). "In a preclinical study, the activity of the high affinity anti-PRLR IgG1 antibody REGN2878-DM1 was evaluated, which induced a potent cell-cycle arrest and cytotoxicity in PRLR-expressing tumor cell lines." (PMID 34745013, 2021). "PRLR-SF inhibits the proliferation of PDAC cells (AsPC-1 and BxPC-3) in vitro and tumor growth in vivo." (PMID 33664869, 2021). "ABBV-176 binds to PRLR, is rapidly internalized, and delivers a potent PBD cytotoxin to tumor cells." (PMID 34107902, 2021). "In contrast, immunofluorescence of tumor tissues in PRLR-DbsAb treated mice showed more CD8+ T lymphocytes distributing dispersedly around the tumors and more surviving T cells in tumor tissues." (PMID 32398042, 2020). "Our previous finding demonstrated that SSM2 and SSM3 cells display persistent prolactin receptor signaling with activation of JAK2, STAT3 and STAT5A/5B, and that pharmacological inhibition of pJAK2 increased SSM2 and SSM3 tumor cell apoptosis." (PMID 27391074, 2016). "Hence, we propose that chronic lack of physiological proapoptotic and antiproliferative actions of PRL, and/or changes in PRLR expression, could contribute to alterations in anterior pituitary cell renewal, leading to pituitary hyperplasia and, eventually, tumor development." (PMID 24859278, 2014). "Analysis of tumor tissue composition, based on the EcoTyper deconvolution tool, revealed that PRLR-high tumors (T3) had an abundant representation of the CE1 signature compared to PRLR-low tumors (T1, Padj < 0.001)." (PMID 40723262, 2025). "In addition, bsAbs can enhance payload internalization and intracellular trafficking by targeting transmembrane proteins, such as the prolactin receptor (PRLR), CD63, or cytokine receptors, thereby increasing uptake into tumor cells." (PMID 41250091, 2025). "Likewise, G129R, a PRL mimics that competes with PRL for binding PRLR, effectively antagonizes PRL but demonstrates limited anti-tumor effects." (PMID 38898487, 2024). "Despite promising preclinical data, the clinical-grade anti-PRLR antibody LFA102 showed no relevant clinical antitumor activity in clinical trials in either tumor type." (PMID 37208719, 2023). "A recent study demonstrated that PRLR-SF reduces nucleotide synthesis by inhibiting the pentose phosphate pathway (PPP) through the NEK9-Hippo pathway in PDAC cells and in xenografted tumors in mice, hindering proliferation and tumor growth." (PMID 37880792, 2023).
tumor (continued). "This was consistent with a recent study demonstrated that both the tumor antigen PRLR and T cell surface CD3 antigen could recruit and activate T cells to kill PRLR expressing BRCA cells." (PMID 35739271, 2022). "The anti-tumor activity of ABBV-176 was therefore evaluated in an expanded set of primarily, but not exclusively, TNB PDX tumor models that express a range from weak to moderate PRLR." (PMID 34107902, 2021). "Recently, we and others showed that prolactin promotes tumor metastasis in vivo; in our study, we more specifically showed it was prolactin working through the long rather than short forms of the PRLR." (PMID 34375938, 2021). "•Knockdown of the long form of the prolactin receptor therefore seems to have an intra-tumor immunotherapeutic effect without effect on peripheral Treg function." (PMID 34375938, 2021). "Here, we identified, for the first time, that PRLR-SF reduces nucleotide synthesis in PDAC cells via the Hippo pathway, which inhibits the pentose phosphate pathway (PPP) to prevent PDAC cell proliferation and tumor growth." (PMID 33664869, 2021). "It is fair statement that the precise role of PRL and its receptor in tumor biology is not yet clear but the present results taken together with previous investigations support a role for PRL/PRLR as being an onco-modulatory factor." (PMID 34358244, 2021). "PRLR-SF inhibits PDAC cell proliferation, colony formation, and the development of xenograft tumors in mice, indicating that this isoform somehow prevents tumor progression." (PMID 33664869, 2021). "Anterior and dorsal prostate lobes displayed the highest Stat5a/b deletion efficiency with no overt compensatory activation of other PRLR signaling cascade at 6 months of age; hence the development of tumor hallmarks was markedly reduced." (PMID 31269779, 2019). "While in the general population tumour PRL/PRLR expression did not correlate with patient survival, biological sex-stratified analyses revealed that male patients with PRL+/PRLRHIGH GBM performed worse than PRL+/PRLRLOW GBM." (PMID 31862900, 2019). "Other genes annotated on chromosome 20 are involved in mammary gland metabolism (GHR, OXCT1), antibody production and phagocytosis of bacterial cells (C6, C7, C9, C1QTNF3), tumor suppression (DAB2), involution of mammary epithelium (OSMR) and cytokine regulation (PRLR)." (PMID 25658712, 2015). "As compared to the results for the 80 kDa PRLr product the 2 tumours with barely detectable Ser9-phosphorylated GSK3β lacked the PRLr 80 kDa product." (PMID 22606260, 2012). "Strong PRLr expression was detected in 24 tumours, while 5 had weak expression only and 7 were negative." (PMID 22606260, 2012). "Out of the 6 tumours with weak Ser9-phosphorylated GSK3β,3 lacked and one had weak PRLr 80 kDa expression." (PMID 22606260, 2012). "Because of PRLR expression in a vast majority of tumour specimens and its negative impact on overall survival, the receptor represents a novel prognosticator and a promising drug target for patients with SCCHNs." (PMID 21505459, 2011). "In conclusion, the present study indicates that PRLR is widely expressed in SCCHNs and that high expression of PRLR in tumour tissue is an independent negative prognostic factor for overall survival in SCCHN patients." (PMID 21505459, 2011). "Previous work using B6.2, a PRLR monoclonal antibody characterized in our laboratory that is unable to distinguish the various isoforms, indicated a lack of correlation between PRLR expression and tumor grade, size or axillary lymph node status." (PMID 21144038, 2010). "Tumour-related cell death can be regulated through autophagy and apoptosis by targeting PRL/PRLR, while the combination of PRL and PRLR has a dose–response relationship: a low concentration of PRL promotes the secretion of PRLR, whereas a high dose of PRL inhibits PRLR." (PMID 37833858, 2023). "Therefore, PRLR-SF might play an important role in metabolic reprograming, thus preventing PDAC tumor progression." (PMID 37880792, 2023).